SST (somatostatin)
Diseases named in the same sentence as SST in open-access papers (continued):
Sharing a sentence is not in itself a finding about the gene and the disease.
breast carcinoma (21 papers, 1997 to 2025). "Diagnostic somatostatin radiotracers, such as the ones evaluated in this study, can identify breast cancer lesions and monitor response to therapy by PRRT." (PMID 29503845, 2017). "Most importantly, the overexpression of SSTR5’s truncated form, sst5TMD4, in breast cancer model increases the pro-angiogenic factors, as well as the number of blood vessels, and is associated with the proliferation of and treatment response to SST analogs." (PMID 38203605, 2023). "Although this is unlikely to have diagnostic or prognostic significance, SSTR2-specific somatostatin analogues may have therapeutic potential in breast cancer." (PMID 9062398, 1997). "This section first describes the expression of SSTR subtypes in breast cancer and then the use of SST and its analogs as a potential therapeutic alternative in treatment of breast cancer." (PMID 38203605, 2023). "Over the years, various SST analogues have been used as antiproliferative agents in the treatment of breast cancer." (PMID 38203605, 2023). "It has been shown that the combination of curcumin with different drugs, like somatostatin, has cytostatic activity by the induction of changes in the composition of fatty acid in the membrane of breast cancer cells." (PMID 33572626, 2021). "They demonstrated that SST-DNL had significantly higher antitumour efficacy in breast cancer models compared to DNL and free DN and increased apoptosis was observed in breast cancer cells in SST-DNL treated groups." (PMID 34512761, 2021). "Two articles have highlighted the positive effects of somatostatin analogs on reducing drainage volumes and the incidence of lymphoceles following axillary node dissection in breast cancer." (PMID 27280398, 2016). "In addition to the crucial role of radiolabeled SST analogs in breast cancer imaging, the SSTR antagonist has also been proposed as a potential candidate for breast cancer imaging." (PMID 38203605, 2023). "SST and SSTRs are well expressed in breast cancer cells and autopsy breast tumor tissues." (PMID 38203605, 2023). "Taken together, with all of these incidences, it is evident that SST and its receptors are of importance, and further advancements could be made to target breast cancer using specific agonist/antagonist combinations." (PMID 38203605, 2023). "Importantly, compound 4-MMI yielded a nearly fourfold inhibition of 4T1 breast carcinoma metastasis, comparable to the effect exerted by Roneparstat (=SST), a well-characterized heparin-like heparanase inhibitor." (PMID 34199150, 2021). "Despite this limitation, it seems reasonable that a compensatory increase in CORT levels in SST-KO mice could contribute, at least in part, to the low incidence of mammary tumors in SST-KO mice on a LF diet." (PMID 26956474, 2016). "Moreover, immunoreactive SST has been identified, by immunohistochemistry, in 30% of breast cancer samples and in several breast cancer cell lines." (PMID 16519802, 2006). "This is the first study that not only systematically analyses the regulation of SSTR by E2 and Tam in breast cancer cells at both the mRNA and protein levels, but also demonstrates how this translates into changes in cancer cell proliferation control with somatostatin analogs." (PMID 16018813, 2005). "Based on these data, it is possible that, in the future, chimeric compounds combining somatostatin with other compatible hormones, could be used, especially in the case of multi-hormone-dependent tumors, such as breast cancer and prostate cancer and ovarian cancer." (PMID 39329930, 2024). "The biological effects of SST are mediated by five receptor subtypes (SSTR1–5), which are expressed in a variety of tumors including breast cancer." (PMID 30513833, 2018). "For instance, a 111In-/90Y-labeled SST analogue, namely DOTA-d-β-Nal1-lanreotide (Dotalan®), has been shown to bind to a broad range of primary human tumors and tumor cell lines including breast cancer cells, presumably through SSTR2-5." (PMID 30513833, 2018).
breast carcinoma (continued). "In breast cancer cells MCF-7, the cytotoxic effect of somatostatin is dependent on SHP-1 and results from caspase 8 activation, cell acidification and mitochondrial dysfunction." (PMID 21143993, 2010). "Furthermore, using breast cancer MCF-7 cells, SHP-1 dependency was revealed in SST-mediated apoptotic signaling via the activation of SSTR subtypes." (PMID 38203605, 2023). "Somatostatin (SST) and cortistatin (CORT), two highly related pleiotropic neuropeptide hormones, have been shown to inhibit proliferation and invasion of breast cancer and other cell types, suggesting their potential value to treat various endocrine-related tumors." (PMID 26956474, 2016). "However, at the end of the study (47 weeks of age), SST-KO mice fewer mammary ducts, which could help to explain the scarce incidence of DMBA-induced mammary tumors." (PMID 26956474, 2016).
gastric cancer (19 papers, 1992 to 2025). A primary or metastatic malignant neoplasm involving the stomach. "The H. pylori infection causes an imbalance between somatostatin and gastrin, which promotes chronic inflammation and the development of gastric cancer." (PMID 39234535, 2024). "From the results, we found that inhibition of SST promotes cell proliferation, which suggests that DNA methylation-associated SST suppression possibly contributes to the gastric cancer progression." (PMID 30778372, 2018). "In conclusion, SST promoter methylation is a common event in human gastric cancer and is connected with a decrease in SST protein and RNA levels and associated with gastric carcinogens." (PMID 24260078, 2013). "In summary, the present study demonstrated that SST promoter methylation is frequently observed in gastric cancer tissue and is associated with a decrease in SST protein expression." (PMID 24260078, 2013). "The association between SST protein and RNA levels and SST methylation and gastric cancer were also analyzed." (PMID 24260078, 2013). "The imbalance between somatostatin and gastrin further leads to chronic inflammation and the occurrence of gastric cancer." (PMID 39234535, 2024). "In clinical studies, SST and its analogs have proven to be effective on anti-angiogenesis and pro-necrosis and apoptosis in gastric cancer patients." (PMID 38203605, 2023). "Our previous comprehensive bioinformatic analysis of aberrantly methylated differentially expressed genes showed that the SST is a hub gene in gastric cancer (GC) and colorectal cancer (CRC)." (PMID 35242243, 2022). "Up-regulation miR-576-5p or inhibition of SST has upturned the biological effects of LINC01133 in gastric cancer cells." (PMID 36042493, 2022). "Studies with other gastric cancer cell lines showed higher SST mRNA levels upon 5-AZA-dC in a subset of the tested cell lines, suggesting cell line-specific responses." (PMID 33085037, 2021). "This was further supported in a recently published paper, showing that knock out of SST in the BGC823 gastric cancer cell line resulted in an increased capacity for migration and invasion in vitro." (PMID 33085037, 2021). "Hypermethylation of the SST promoter in gastric cancers results in decreased mRNA and protein expression, thereby reducing somatostatin's ability to inhibit tumor growth." (PMID 34112938, 2021). "Contradictory to this, reduced SST mRNA and SST protein expression levels have been described in gastric carcinoma samples throughout multiple studies using larger cohorts of patients." (PMID 33085037, 2021). "We found that inhibition of SST can significantly promote cell proliferation, which suggests that down-regulation of SST is involved in stomach cancer progression." (PMID 30778372, 2018). "Consistent with this, a recent study showed that SST promoter hypermethylation is common in human esophageal adenocarcinoma, gastric cancer, and colon cancer." (PMID 25734919, 2015). "SST promoter methylation is a common event in human gastric cancer as well; it is connected with a decrease in SST protein and mRNA levels and associated with gastric carcinogens." (PMID 25723531, 2015). "Somatostatin (SST) is a gut peptide that is able to inhibit the growth of tumor cells in gastric cancer and other types of cancer." (PMID 24260078, 2013). "The RT-PCR analysis indicated that the mRNA levels of SST (0.218±0.183 vs. 0.456±0.331; P<0.001) and SSTRs in the gastric cancer group were lower compared with those of the normal gastric tissue group." (PMID 24260078, 2013). "The protein levels of SST were decreased in the gastric cancer group compared with those of the normal group (5.091±0.994 vs. 7.399±0.956 pg/mg; P<0.01)." (PMID 24260078, 2013). "The present study investigated the mRNA and protein levels of SST and SST receptors (SSTRs) in human gastric cancer, and detected the DNA methylation of the SST promoter." (PMID 24260078, 2013).
gastric cancer (continued). "The protein levels of SST were detected using a radioimmunoassay in 102 human gastric tissue specimens (51 pairs of samples from 51 gastric cancer patients, each pair of samples included a cancer tissue and a normal tissue sample)." (PMID 24260078, 2013). "Recently, SST promoter methylation has been found in various cancers, including gastric cancer, cervical cancer and colon cancer." (PMID 21962230, 2011). "High affinity receptors for somatostatin were expressed by one gastric carcinoma (Kd = 0.9 nM; Bmax = 0.23 pmol mg-1 protein)." (PMID 1354473, 1992). "Moreover, it has been reported that SST and its analogs inhibit the growth of gastric cancer cell lines, indicating a positive role of SST in regulation of gastric tumour progression." (PMID 38203605, 2023). "Thus, LINC01133 up-regulation can suppress development of gastric cancer through decreasing expression of miR-576-5p and enhancing SST levels." (PMID 36042493, 2022). "On the other hand, the regulation of SST expression in gastric cancer has been subject to research." (PMID 33085037, 2021). "Moreover, a high DNA methylation level of the SST promotor and its assocation with undetectable SST expression has been described in seven gastric cancer cell lines." (PMID 33085037, 2021). "However, the role of DNA methylation in decreasing the expression of SST in gastric cancer remains undetermined." (PMID 24260078, 2013). "Thus, it is hypothesized that a lower level of SST leads to a higher level of gastrin, which increases gastric cancer occurrence." (PMID 35650297, 2022). "This study aimed to simultaneously explore the relationships between the SST methylation and the risks of three GIT cancers (esophageal cancer (EC), gastric cancer (GC), and colorectal cancer (CRC)) and to evaluate its diagnostic value." (PMID 35242243, 2022). "The present study investigated the expression of SST, SST mRNA and SSTR mRNA in gastric cancer and utilized methylation-specific PCR (MSP) technology for the analysis of SST promoter DNA methylation." (PMID 24260078, 2013). "The distribution of the positive methylation cases for SST in patients with gastric cancer did not correlate with the age or gender of the patients or the size, location and type of the carcinoma." (PMID 24260078, 2013). "Another study based on differentially methylated regions of the SST in CRC by The Cancer Genome Atlas (TCGA) database analysis indicated that the average methylation rate of the SST 1stExon was negatively correlated with the SST expression in CRC and gastric cancer." (PMID 38540191, 2024). "Thus, and although much less is known about their role in tumoral cells, it seems that somatostatin and SSAs can reduce VEGF production from some types of tumoral cells such as gliomas, gastric carcinomas or pancreatic cancer, acting through the sst2 receptor subtype." (PMID 27507050, 2016). "We performed Quantitative Real-time PCR (qPCR) on 6 up-regulated genes (COL1A, BGN, SPP1, MELK, IGFBP4, SPARC) and 4 down-regulated genes (PGC, SST, MT1X, S100P) to verify our data in gastric cancer tissues (Tumor) and noncancerous tissues (Normal)." (PMID 25928635, 2015).
meningioma (19 papers, 2013 to 2025). A generally slow growing tumor attached to the dura mater. "The presence of SSTRs in human meningiomas has been confirmed by several authors, and SST‐analogues have been applied in the therapy of human meningiomas." (PMID 39011594, 2024). "In a study by Graillon el al.comparingthe effects of pasireotide to those of octreotide in vitro on meningioma primary cell cultures, combining an SST analog with an mTOR inhibitor like everolimus has demonstrated efficacy in treating aggressive meningiomas." (PMID 38919490, 2024). "Since the potent cell-proliferation inhibiting effect of somatostatin (SST), the aim of this study was to investigate in vitro the effects of octreotide, as SST analog, in the viability of canine meningioma." (PMID 39055601, 2024). "The known antiproliferative effect of SST in pancreatic, pituitary and breast tumours and mapping of SSTRs in meningioma and gliomas indicate an effective therapeutic value of SST in the treatment of these tumours." (PMID 38203605, 2023). "The mapping of SSTRs in various brain tumours led to the application of radiolabeled imaging and targeting of these tumours using radiolabeled SST analogs in gliomas and meningioma." (PMID 38203605, 2023). "For example, the peptide octreotide, a somatostatin agonist, has been used in combination with an mTOR inhibitor for aggressive and recurrent meningiomas where they have shown to be effective and well tolerated." (PMID 37835469, 2023). "Tracers directed to the somatostatin/SSTR2a receptor seem the most promising, since the majority of meningiomas express this receptor." (PMID 33694025, 2021). "Overall, these data highlight the potential utility of the pan-somatostatin molecule pasireotide in treating meningiomas." (PMID 28903425, 2017). "The high incidence of SST receptors in human meningiomas is known since decades and the inhibitory role of SST in the control of proliferation in primary cultures of human meningioma cells has been described." (PMID 23476673, 2013). "Membranous staining was present in all canine and 83% of feline meningiomas, indicating that SST‐analogue therapy may be a viable option for treating meningiomas as it was found that membrane staining is important for therapeutic success." (PMID 39011594, 2024). "This difference may be explained by the lack of histological diagnosis of all cases (with the impossibility to know the histological features, such as typical or atypical meningiomas usually characterized by different SST expression nature)." (PMID 35888635, 2022). "Additionally, a decrease in DNA synthesis was observed when somatostatin was applied to primary cell cultures derived from meningiomas." (PMID 34601710, 2022). "On the contrary, increase of cell growth may be induced by somatostatin, since meningiomas mostly express somatostatin receptors that repress the formation of cAMP." (PMID 31671850, 2019). "SSTRs are widely expressed in canine and feline meningiomas, thereby encouraging further studies investigating SSTR expression to conduct trials about the effect of adjunctive therapy with long‐acting SST‐analogues." (PMID 39011594, 2024). "So far, somatostatin agonists and progesterone antagonists and cytotoxic and hormonal agents have not been highly effective in cases of high-grade meningiomas." (PMID 40075786, 2025). "No other studies specifically investigating the use of somatostatin analogs to depict the effects of radiotherapy on meningiomas were found in the literature." (PMID 36449758, 2022). "However, our study did not specifically investigate the efficacy of different analogues, and no SST‐analogues have been used for the treatment of feline meningiomas." (PMID 39011594, 2024).
meningioma (continued). "The rationale for the use of SST analogs in the control of intracranial meningioma is supported by the widespread expression of SST receptors in this tumor and by the fact that currently no adjuvant therapy for meningioma is available in patients with unresectable or radioresistant lesions." (PMID 23476673, 2013).
adenoma (16 papers, 2010 to 2026). A neoplasm arising from the epithelium. "It has been demonstrated that the efficacy of these drugs correlates with the expression of SST in the adenomas, especially in acromegaly." (PMID 39473262, 2025). "On the other hand, in a hyperplastic context, it has been suggested that endogenous SST does play a role in suppressing the expansion of the somatotroph population and slowing adenoma formation in response to ectopic GHRH excess." (PMID 37576961, 2023). "CpG sites within the SST gene were hypermethylated in different stages of tumorous samples, i.e. 94%, 100%, 94% and 57% for adenomas with low-grade dysplasia, adenomas with high-grade dysplasia, CRC and metastatic-CRC, respectively." (PMID 33085037, 2021). "In the present study, nuclear and cytoplasmic SST expression appeared in the majority of parathyroid tumors, with significantly different expression profiles in adenomas, atypical adenomas and carcinomas." (PMID 31336364, 2019). "These receptors provide a promising target for medical treatment of ACTH-producing adenomas with somatostatin analogs." (PMID 30627156, 2018). "These somatostatin analogues have been previously shown to inhibit GH secretion in primary cultures of human GH-secreting adenomas (for reviews, see55, 56)." (PMID 26549306, 2015). "In this setting, somatostatin receptor ligands (SRL), which exert their action by interacting with SST, are an important class of drugs for the treatment of adenomas secreting growth hormone (GH), adrenocorticotropic hormone (ACTH), and thyroid‐stimulating hormone (TSH)." (PMID 39473262, 2025). "However, endogenous SST primarily controls GHRH-induced adenoma formation via modulation of apoptotic and/or cellular senescence pathways in a hyperplastic context." (PMID 37576961, 2023). "However, apart from the SSTR or ZAC1 expressions, differences in the pathogenesis of somatotropinomas and NFPA are also likely to account for the different response to somatostatin analogs in these adenoma subtypes." (PMID 24098585, 2013). "Furthermore, variable sst1–5 expression has been extensively documented and consequently SST analogs have been classically used after adenoma or tumor resection." (PMID 23162532, 2012). "In addition to the expression of SSTR2 mRNA, the expression of SSTR5 mRNA may also influence tumor shrinkage by somatostatin analogs against TSH-secreting adenomas." (PMID 39202532, 2024). "In fact, SST2 mRNA levels in adenomas from these normocortisolemic patients were comparable to those of GH-producing adenomas, which are usually responsive to SST2-preferring somatostatin analogs." (PMID 40452800, 2025). "The expression of both types of SST was calculated for 21 corticotropinomas; in two cases, only SST2 or SST5 receptors were stained due to the limited amount of adenoma tissue." (PMID 39684597, 2024). "Although previous studies have suggested that SSTRs other than SSTR2 are involved in this type of adenomas, studies involving other SST analogues like SOM230 should be further evaluated, as high expression levels of SSTR3 in these adenomas are of great relevance." (PMID 38203605, 2023). "Unlike the dopamine-receptor agonists acting sensitively on prolactinomas, or somatostatin analogs acting on growth hormone-secreting adenomas, pharmacologic options for ACTH-secreting adenomas are limited to drugs targeting pituitary tumors, adrenal glands, or peripheral glucocorticoid receptors." (PMID 33537004, 2020).